TIMP1 (TIMP metallopeptidase inhibitor 1)
Diseases named in the same sentence as TIMP1 in open-access papers (continued):
Sharing a sentence is not in itself a finding about the gene and the disease.
tumor (continued). "Treatment of mice with xenotransplanted canine histiocytic sarcomas using CDV induced overt retardation in tumor progression accompanied by necrosis of neoplastic cells, increased numbers of intratumoral macrophages, reduced angiogenesis and modulation of the expression of MMPs and TIMP-1." (PMID 33808256, 2021). "As the same, knock down of TIMP1 also could slowdown tumor growth in vivo (P < 0.05)." (PMID 34848810, 2021). "Interestingly, four genes (TIMP1, SERPINE1, PLAUR and PTX3) associated with poor overall survival of both LUAD and LUSC patients, are involved in the regulation of ECM remodelling, which plays a key role in the aggravation of tumour malignancy and metastasis." (PMID 34807957, 2021). "Therefore, we speculate that coexpression of MMP-7 and TIMP-1 in tumour tissue may initiate a positive feedback pathway that directly accelerates tumour invasion and progression." (PMID 33005257, 2020). "This suggests different regulatory mechanisms may be applicable between TIMP-1 and IL-6 expression depending upon elements present within various cell types or cancer specific tumor microenvironments, and our results may be specific to this interaction within NSCLC." (PMID 31443242, 2019). "MMP-9 and TIMP-1 expression in the normal mucous adjacent to the tumor might be an effect of the activity of neoplastic cells and their interaction with the adjacent environment as well as inflammatory cell intrusion, which was shown in more than half of the studied specimens." (PMID 31143300, 2019). "Importantly, plasma levels of TIMP-1 protein were found to be significantly elevated in PDAC and CP patients in an unbiased system-wide proteomics approach, which further supports its potential usefulness as a diagnostic tumor marker." (PMID 29394913, 2018). "However, the precise mechanisms linking SIRT1, TIMP1 and tumor-like invading FLSs in RA remains unclear." (PMID 29179491, 2017). "Thus, a merely genotoxic carcinogenesis model such as DEN could fail to reproduce potential tumor promoting effects of TIMP-1 which is upregulated during chronic liver fibrogenesis." (PMID 28386095, 2017). "However, the precise mechanisms linking SIRT1, TIMP1 and the tumor-like invasion of RA FLSs remain unclear." (PMID 29179491, 2017). "In addition, TIMP-1 secretion is increased, which may directly inhibit matrix metalloproteases critical for collagen degradation in the tumor." (PMID 27793045, 2016). "Moreover, inhibiting TIMP-1 function prevented tumor growth in mice, suggesting that TIMP-1 inhibition might be a promising therapeutic strategy for treating TNBC." (PMID 27130446, 2016). "In addition, corresponding tumor biopsies were immunohistochemically stained for TIMP-1 and scored." (PMID 27619981, 2016). "In addition, TIMP-1 secretion is increased, which may directly inhibit several MMPs critical for collagen degradation in the tumor." (PMID 27793045, 2016). "Together, these studies embody an evolving mechanistic model where distinct levels of NO influence and regulate specific signaling mediators within the tumor microenvironment that in turn promote tumor survival and progression, which may include TIMP-1 and Akt signaling as shown in this study." (PMID 22957045, 2012). "Indeed, TIMP-1 knockdown led to a marked increase in tumor burden." (PMID 22230683, 2012). "Such positive-regulatory co-operation of HIF-1α, miR-210, and TIMP-1, all described to correlate with bad prognosis of cancer patients, opens new perspectives of gaining insight into molecular mechanisms of metastasis-inducing evasion of tumor cells from stress." (PMID 22807917, 2012).
tumor (continued). "Moreover, as compared to normal endothelium, tumor endothelium showed gain of function of numerous proangiogenic molecules such as integrin β3, PlGF, VEGFR1, Nur77, Ang2, eNOS, TGFβ, MCP-1, TIMP-1, and t-PA, while loss of function was observed for vessel stability genes such as Ang1 and Tie2." (PMID 22235379, 2011). "However, at the protein level, there was up-regulation of CXCL5/ENA78, CCL20/MIP3-α, IGFBP3, OPN and TIMP1 in tumours and their PN, indicating that these could be early events in the gastric tumorigenesis." (PMID 21092330, 2010). "In addition, our data showed that the expression of MMP-1, 7, 9, 11, 13, 14, TIMP-1, and 2, as a function of the cellular type (tumour cell, fibroblast, and/or inflammatory mononuclear cell) expressing the protein, was significantly associated with a shorter relapse-free survival." (PMID 17342087, 2007). "Crucially, the TIMP1 inhibitor FXR agonist 3 suppressed MSCs-driven BC proliferation in vitro and attenuated tumor growth in PDX models by disrupting the cMet-RAP1 signaling pathway without systemic toxicity." (PMID 42003907, 2026). "Spatial transcriptomics revealed distinct expression patterns of SOX9 and TIMP1 within tumor tissues, supporting the conclusion that SOX9 transcriptionally activates TIMP1 to suppress DC maturation." (PMID 41270217, 2026). "Intersection analysis of these DEGs indicated that the expression of two DEGs (TIMP1, FN1) differed significantly among the three groups, showing an upward trend in expression levels with tumour progression." (PMID 40638546, 2025). "In vivo tumor analysis corroborated these findings, revealing elevated expression of GPX4, GCLC, and GCLM in TIMP1-knockdown tumors." (PMID 40185230, 2025). "Known for its role in aggressive cancers, TIMP1 promotes macrophage polarization via IL-10 and TGF-β secretion, enhancing tumor progression through the PI3K/AKT pathway." (PMID 40299331, 2025). "For instance, TIMP1 promotes RCC metastasis by inducing EMT, while CSN5 facilitates tumor progression through the stabilization of ZEB1, thereby enhancing EMT-mediated tumor spread." (PMID 40002717, 2025). "The specificity of TIMP1 as a CRC driver is supported by its correlation with pathological staging and its overexpression in tumor tissues compared to healthy controls." (PMID 40687427, 2025). "Studies conducted on tumor-bearing animals in vivo revealed elevated levels of tumor-derived factors, including TGF-β, MCP-1, RANK, TIMP-1, and TSP-1, in platelets." (PMID 40647654, 2025). "As a natural regulator of MMP, TIMP1 plays a role beyond merely inhibiting MMP activity; it also influences immune responses, angiogenesis, and tumor cell migration within the tumor microenvironment." (PMID 41465391, 2025). "In contrast, tumor-infiltrating CD8+ T cells increased, and levels of tissue inhibitor of metalloproteinase-1 (TIMP-1), N-cadherin and Snail increased in the metastatic lung." (PMID 41019086, 2025). "Our findings also reveal, for the first time, that TIMP-1, classified among OXSRDEGs, is upregulated in both UC and CRC, with enrichment in tumor signaling pathways, such as TGF-β, probably marking it as a novel anticancer therapeutic target." (PMID 40595862, 2025). "Our analysis revealed that TIMP1 was predominantly expressed across various cell types, particularly stromal cells, while MMP10 and F2RL2 exhibited low expression levels in both non-tumor and tumor cells." (PMID 40777024, 2025). "Tissue inhibitor matrix metalloproteinase 1 (TIMP1) is a matrix metalloproteinase (MMP) that regulates the interaction with the extracellular matrix (ECM), such as cell growth, tumor cell invasion, and metastasis." (PMID 41465391, 2025). "Regarding MMPs, a slight decrease was observed in the expression of MMP-9, and the level of TIMP-1 was increased; however, lower levels of MMP-2 and TIMP-2 were detected in tumorous tissues compared to adjacent healthy tissue samples." (PMID 39062015, 2024).
tumor (continued). "Besides, TIMP1 is reportedly as a tumor-secreted protein that could be detected in the serum." (PMID 38770133, 2024). "In the analysis of circulating tumor cells from patients with advanced stage HGSOC, TIMP1 has been suggested to be used as a therapeutic target." (PMID 38172678, 2024). "Increased expression of vascular endothelial growth factor-A (VEGF-A) and hypoxia-inducible factor-1α (HIF-1α), a tissue inhibitor of metalloproteinases-1 (TIMP-1), was observed in tumorous samples compared to adjacent normal tissues." (PMID 39062015, 2024). "Our results indicate that soluble TIMP-1 augments MHC-I expression in myeloid DCs when exposed to tumor antigens, underscoring its potential role in modulating tumor immunity." (PMID 38777826, 2024). "CTShigh and C1Qhigh TAMs generate immunosuppressive interactions with aDTCs via predominantly secretion of SPP1, FN1, TIMP1, or upregulation of CD74, all of which foster tumor-cell metastasis." (PMID 38460015, 2024). "This autocrine activity of TIMP-1 positions it alongside other key immunomodulatory cytokines such as IFN-γ and TNF-α, known for their efficacy in tumor immunity." (PMID 38777826, 2024). "Remarkably, the supernatant of tumor monocytes was able to induce a higher expression of CRC EGC marker genes (Lcn2, Timp1, Ccl2, and Il6) compared to control BM-derived monocytes in an IL-1R-dependent manner." (PMID 39030280, 2024). "These 6 tumor-exclusive proteins detected in every single sample comprised MARCKSL1, IKBIP, COPZ1, TIMP1, FAM50A and DPM3." (PMID 39681068, 2024). "Strong positive correlations were found between CD31 levels in primary tumor tissue and FABP4+MMP9+MMP2+TIMP1- (r = 0.82, p < 0.05) and FABP4+MMP9+MMP2-TIMP1- (r = 0.67, p < 0.05) populations of plasma sEVs." (PMID 37109070, 2023). "The statistical analysis did not confirm the presence of the correlation between the expression of TIMP1 (p = 0.4306), MMP2 (p = 0.9208) or MMP9 (p = 0.8674) in blood before surgical removal of tumor tissue and survival of patients with NSCLC." (PMID 37509417, 2023). "Differentiated cells at days 26 and 30, characterized by negligible expression levels of TIMP1, MMP9 and CD44, were unable to induce tumor growth." (PMID 36906579, 2023). "TIMP1, together with its binding protein CD63, has emerged as a predictive biomarker with regard to tumor therapeutic response and spreading." (PMID 36906579, 2023). "The methylation of HOXA1, IGFBP2, PTX3, TIMP1, SHOX2, and SH2D4A decreases with increasing tumor grade." (PMID 37091145, 2023). "Among these newly identified splicing isoforms, TIMP1 Δ4-5 transcript (exon 4–5 exclusion of tissue inhibitor matrix metalloproteinase 1) was significantly downregulated in CRC and suppresses tumor cell growth and metastasis." (PMID 37735421, 2023). "A similar trend was observed in tumor grade, where the expression levels of CENPA and TIMP1 were positively correlated with grade and that of MYCN was negatively correlated." (PMID 37213288, 2023). "On the 24th hour and on the 9th day after, tumour induction blood was collected to estimate levels of VEGF, NO, TIMP-1 and IL-2 (interleukin-2)." (PMID 38067491, 2023). "As a regulator of ECM homeostasis, tissue inhibitor of metalloproteinases-1 (TIMP-1) is involved in inflammation and tumor progression." (PMID 38023616, 2023). "In the presented study, the expression of MMP2, MMP9 and TIMP1 genes was assessed in the blood of NSCLC patients at three time points, before the tumor removal surgery, 100 days after surgery and one year after surgery, and in the tumor tissue." (PMID 37509417, 2023). "TIMP1, PGF, FSTL3, SNAI1, and FOXC1 were highly expressed in CAFs with high stemness scores in the tumor intestinal tissues." (PMID 37017587, 2023).
tumor (continued). "According to our results, piperine reduced cell migration by regulating MMP2 and MMP9 and their action on their respective antagonists, as TIMP1 and TIMP2 inactivate metalloproteinases and prevent their action, triggering a reduction in tumor cell migration." (PMID 36678600, 2023). "TIMP1 has been shown to be involved in the EMT process of ccRCC and can enhance tumor cells metastasis." (PMID 36959648, 2023). "The expression levels of MMP9, VWF, VEGFA, SERPINE1, and TIMP1 in ccRCC tissues were higher than those in normal tissues, while the expression of EGF in tumor tissues was lower." (PMID 36959648, 2023). "We found that TIMP‐1 expressed in hASCs regulated the deposition of ECM on the surface of spheroids, as well as the penetration of drugs into the 3D tumor model." (PMID 35600659, 2022). "TIMP-1 secretion was also found to increase in aHSC-CM, which enhances the deposition of ECM to generate the tumor stroma and further abrogate the immune attack." (PMID 36142683, 2022). "We detected more abundant levels of sICAM-1, CXCL10, CXCL1, CCL5, TIMP-1 and TNFα in tumours treated with VV-αCEA TCE, compared to tumours treated with VV-CTRL or PBS." (PMID 36405739, 2022). "We also identified unique signatures in tumour samples after VV-αCEA TCE treatment, including increased levels of CCL1, IFNγ, IL-1a, IL-1b, TIMP-1, and TREM-1." (PMID 36405739, 2022). "Previous studies have shown that a high expression of C3, TIMP-1, and AHSG genes in tumors can promote tumor cell proliferation and tumor deterioration." (PMID 35935258, 2022). "The same tumor cells that secrete MMPs also synthesize TIMPs, the imbalance of MMP-9: TIMP1 makes tumor cells more invasive." (PMID 36158681, 2022). "More specifically, we have detected increased levels of sICAM-1, CXCL10, CXCL1, CCL5, TIMP-1 and TNFα in tumours treated with VV-αCEA TCE, compared to tumours treated with VV-CTRL or PBS." (PMID 36405739, 2022). "For instance, In tumor-immune interface-3, pro-tumor expression markers are TIMP1, a member of MMPs involved in the degradation of the extracellular matrix, whereas IGFBP4, PFDN5, CD63 repress tumor progression." (PMID 35835774, 2022). "They further found that MMP-10, TIMP-1, and TIMP-2 were correlated to tumor size, with TIMP-2 had the most significant impact on tumor size." (PMID 35586209, 2022). "We observed expression by tumor cells of thrombospondin (THBS1) and tissue inhibitors of metalloproteinases (TIMP1 and TIMP2), secreted factors involved in extracellular matrix remodeling." (PMID 36028490, 2022). "MT2A, TIMP1, and GFAP are more highly expressed in tumor cells and are down-regulated in the periphery." (PMID 35327982, 2022). "TIMP-1 expression was cytoplasmic within tumor cells, whereas CD44 was seen as positive staining of cytoplasmic membranes of tumor cells and within multiple cell types in the stroma." (PMID 36230997, 2022). "The presence of tissue inhibitors of matrix metalloproteinases 1 and 2 (TIMP-1 and TIMP-2) was also confirmed, further suggesting a complex regulatory role of ectosomes within the tumor microenvironment." (PMID 35406748, 2022). "When correlating MMP-1, MMP-2, MMP-9, TIMP-1, and TIMP-2 expression in tumor tissue in non-invasive and invasive PTC, we report significant positive correlation between TIMP-2 and MMP-2 in the non-invasive tumor group (rho = 0.378, p = 0.039)." (PMID 36551933, 2022). "As indicative of an enriched immune tumor microenvironment, we found CXCR3, ZAP70 and PTPN22; whereas others, such as TIMP1 and MAP2K3, had higher correlation with endothelial markers indicative of a tumor-induced angiogenic process." (PMID 35875157, 2022). "We validated the transcriptional expression of identified 6 key fibrosis factors (PCOLCE2, APOD, APOE, TIMP1, HTRA3 and MT1A) in tumor and normal tissues obtained from 20 PTC patients." (PMID 36387901, 2022).
tumor (continued). "KDM1A can apparently inhibit the expression of TIMP1 by demethylating H3K4ME2 in the TIMP1 promoter region, activating MMP9, which is responsible for tumor migration and PTC invasion through this pathway." (PMID 34055497, 2021). "In our in vivo model, however, properdin-deficient mice, when inoculated with logarithmically growing B16F10 cells, showed decreased levels in blood of the chemoattractants C5a and CCL2 and in tumour of the mediators CCL2, CCL3, IL-13, and TIMP-1." (PMID 33494138, 2021). "Further, the TIMP1 and CXCL13 proteins were significantly related to the tumor immune infiltration of CD8+ T cells." (PMID 33579281, 2021). "TIMP1+M3 was the unique subtype enriched in MSC2, suggesting its potential ability to promote tumor progression." (PMID 34659209, 2021). "To verify the results of our data analysis, we extracted total RNA from different tumour cell lines (HCT116, SW480, HT29, LOVO, RKO, DLD-1) and the normal epithelial colon cell line NCM460 and measured the mRNA expression levels of TIMP1, PLCG2, BDNF and IL13." (PMID 35003085, 2021). "The protein expression of galectin-3, TIMP-1, and NAG-1 was higher in tumor tissues than in normal tissues." (PMID 34208730, 2021). "The mean mRNA expression of TGFB3 (P = 0.0313), TIMP1 (P = 0.0469), GREM1 (P = 0.0156), and CTGF (P = 0.0313) were all increased in tumour stroma EVs compared to normal stroma EVs." (PMID 34596356, 2021). "The genes TIMP1, MAGEB17, CA3, and KRT75 expressions are relatively lower with sequence read at <100 in both cultured cells and tumor samples." (PMID 33808801, 2021). "Tumor immune infiltration analysis results showed that TSPAN11, GPRC5B, TIMP1, and CXCL13 protein levels were significantly positively correlated with CD4+ T cells, macrophages, neutrophils, and dendritic cells." (PMID 33579281, 2021). "The tumor cells secreted a few C/Cs on the panel, including exclusive secretion of IL-11, and shared secretion of CX3CL1, LIF and TIMP-1 with the fibroblasts." (PMID 34572807, 2021). "The expression of TIMP-1 and TIMP-2 was detected in stromal cells, and TIMP-3 expression in tumor epithelial cells, in the infiltrative area." (PMID 34204372, 2021). "A study investigating the serum levels of TIMP-1 and MMP-7 in patients with metastatic CRC found that serum MMP-7 together with TIMP-1 can be used as effective tumour markers for detecting metastatic CRC." (PMID 33005257, 2020). "For instance, pairwise comparison of primary tumor cell line #1 with recurrent tumor cell line #3 identified a cluster (Cluster #7) distinguished by high expression of mesenchymal genes, including Vimentin, S100A6, and Timp1." (PMID 33024122, 2020). "In the first study, the clinicopathological role of TIMP-1 and TIMP-2 in HL was investigated by examining tumor samples obtained from 68 patients." (PMID 32751899, 2020). "Genes specifically expressed by tumor cells, like tenascin C (TNC), periostin and TIMP1 (Tissue inhibitor of metalloproteinases 1) can shape the brain parenchyma." (PMID 32570988, 2020). "In LGG tumor tissues, EMP3, IGFBP2, TIMP1 and SERPINE1 are all highly expressed, compared with normal brain tissues." (PMID 32328202, 2020). "And IGFBP2, EMP3, TIMP1 and SERPINE1 are all highly expressed in LGG tumor tissues compared with normal brain tissues." (PMID 32328202, 2020). "On the one hand, expression of MMP-7 gradually increases with tumour progression, and eventually, highly expressed MMP-7 induces expression of TIMP-1 to regulate proteinase reactions." (PMID 33005257, 2020). "TIMP1 is known to regulate the activity of MMP9, which promotes tumor migration due to extracellular matrix degradation." (PMID 32423054, 2020).